BDNF (brain derived neurotrophic factor)
Diseases named in the same sentence as BDNF in open-access papers (continued):
Sharing a sentence is not in itself a finding about the gene and the disease.
diabetes (278 papers, 2010 to 2026). "It has also been reported that there is an association between reduced BDNF levels and impaired glucose metabolism in patients with type 2 diabetes mellitus." (PMID 39857710, 2025). "These disruptions in neurotransmitter function, alongside the reduced release of brain-derived neurotrophic factor (BDNF) in diabetes mellitus, further amplify the risk of CI in affected individuals." (PMID 40726602, 2025). "Diabetes is associated with changes in levels of BDNF, which leads to a plethora of neurological complications, highlighting the importance of transitioning through the health perspectives of a DN patient." (PMID 41142318, 2025). "Disruptions in the function of certain neurotransmitters, such as AChE, combined with reduced release of BDNF in type 2 diabetes mellitus, significantly heighten the risk of CI in affected individuals." (PMID 40726602, 2025). "In the STZ-induced diabetes model, impaired basal synaptic transmission and failure of gLTP were linked to reduced levels of brain-derived neurotrophic factor (BDNF)." (PMID 41187128, 2025). "This supports the potential of enhancing BDNF expression as a therapeutic strategy to mitigate diabetes-associated neuroinflammation." (PMID 40726602, 2025). "This decrease in BDNF secretion is associated with the increased systemic glucose in diabetes, as SCs in culture under hyperglycemic conditions show reduced BDNF levels." (PMID 38236305, 2024). "Diabetes is associated with low levels of BDNF and reduced neurogenesis in the hippocampus, and reduced serotonin levels in the hypothalamus, cortex, and hippocampus." (PMID 38279738, 2024). "The presence of diabetes was ascertained, and sBDNF levels and the presence of the BDNF Val66Met polymorphism were measured in 969 patients within 2 weeks after an ACS episode." (PMID 35459929, 2022). "We investigated the individual and interaction effects of diabetes and BDNF-related markers, namely the serum BDNF (sBDNF) level and the BDNF Val66Met polymorphism, on suicidal ideation (SI) in ACS patients." (PMID 35459929, 2022). "In the present study, the association between BDNF and frailty persisted even after excluding individuals with diabetes." (PMID 36329115, 2022). "Although both diabetes and the brain-derived neurotrophic factor (BDNF) pathway are closely associated with ACS and suicide, the effects of these factors on suicidal behavior in ACS patients have not been assessed." (PMID 35459929, 2022). "The presence of both diabetes and a low sBDNF level or the BDNF Met/Met genotype was associated with acute SI, with multivariate logistic regression analyses revealing significant interaction effects." (PMID 35459929, 2022). "The association between diabetes and SI in patients with the BDNF Met/Met genotype was dependent on fasting glucose levels." (PMID 35459929, 2022). "Another cohort study also showed that low levels of BDNF is an independent risk factor for diabetes and obesity." (PMID 36329115, 2022). "Diabetes was significantly associated with both acute and chronic SI only in the presence of the BDNF Met/Met genotype, and a significant interaction with acute SI but not with chronic SI was found after adjustment for the relevant covariates." (PMID 35459929, 2022). "In fact, obesity, metabolic syndrome, type 2 diabetes mellitus, and CV diseases including HF were associated with decreased serum levels of BDNF." (PMID 33520013, 2021). "Several studies have investigated the association between BDNF and diabetes in experimental and clinical diabetes." (PMID 32405353, 2020). "Among these regulators, BDNF has been considered to be linked with the prognosis and progression of diabetes." (PMID 33029194, 2020). "The association between BDNF and diabetes has been investigated in experimental and clinical diabetes, and low BDNF serum levels have been reported in diabetic humans and mice." (PMID 32405353, 2020).
diabetes (continued). "A cross-sectional study cannot interpret a causal relationship between serum BDNF levels and retinopathy due to diabetes." (PMID 33457130, 2020). "Our present results indicate that diabetes-associated neuroinflammation, reduced BDNF levels and impaired BDNF signalling can be effectively reversed by an ARB." (PMID 31053872, 2019). "Details on the molecular mechanisms underlying the effect of BDNF and TrkB on diabetes induced GI remodeling are needed to be explored as well." (PMID 29930382, 2018). "Multiple linear regression analysis revealed that elderly age, the presence of diabetes mellitus, and vWF levels were independently associated with low BDNF levels in stable CAD patients." (PMID 29409455, 2018). "Recently, our clinical research from patients with stable coronary artery disease showed that the plasma BDNF levels were strongly associated with the presence of diabetes mellitus, so we explored the BDNF expression of HG- injured HUVECs." (PMID 30459620, 2018). "There were no statistically significant group differences on sociodemographic variables, body composition, BDNF levels, or diabetes risk factors." (PMID 30363954, 2018). "Low levels of plasma BDNF have been associated with dementia, diabetes, depression and coronary syndrome." (PMID 28161695, 2017). "It is noteworthy that diseases other than RA but combining as RA impaired cognition and high cardiovascular risk such as hypertension and diabetes were reported to induce BDNF downregulation in neurons, endothelial cells or both." (PMID 29375397, 2017). "Reduction of retinal levels of BDNF has also been reported in animal models of diabetes, probably caused, at least in part, by oxidative stress." (PMID 27123463, 2016). "In our cross-sectional observational study of 4463 community-living older adults, serum BDNF was associated with a decline in story memory and digit symbol substitution test scores, even when adjusted for sex, age, education, diabetes, and current smoking." (PMID 24782766, 2014). "After adjustment for sex, age, education level, diabetes, and current smoking, serum BDNF was associated with poorer performance in the story memory, and digit symbol substitution task scores." (PMID 24782766, 2014). "According to recent studies, BDNF is associated with systemic inflammatory conditions, such as diabetes, acute coronary syndrome, and atherosclerosis." (PMID 25587547, 2014). "We showed that BDNF genetic variation was associated with pre-diabetes independently of BMI, and in accordance with its association with T2DM and hyperglycemia." (PMID 23431394, 2013). "In the 1,5-isoquinolinediol-treated diabetic rats, the decrease in BDNF, synaptophysin, and GS caused by diabetes was attenuated by about 50%, 34%, and 50%, respectively." (PMID 24347828, 2013). "The findings suggest that the early retinal neuropathy of diabetes involves the reduced expression of BDNF, whose deficiency is associated with a number of neurodegenerative disorders." (PMID 23766563, 2013). "Furthermore, BDNF has central appetite suppression effects and is associated with diabetes mellitus and associated psychiatric and neurological symptoms." (PMID 39941545, 2025). "The current study indicated that WJMSC-CM could alleviate the decrease of BDNF caused by STZ-induced diabetes." (PMID 37081849, 2023). "A low peripheral BDNF level is associated with diabetes-related complications." (PMID 35459929, 2022). "Because diabetes-related complications are related to a higher risk of SI32, diabetes may be predictive of SI only in subjects with low sBDNF levels or with the BDNF Met/Met genotype due to the high burden of those complications." (PMID 35459929, 2022). "Recently diagnosed ACS is associated with severe emotional and physical distress, and the interaction effects of diabetes and altered BDNF-related markers may amplify these precipitating causes of acute SI." (PMID 35459929, 2022).
diabetes (continued). "Our study suggests that the combination of diabetes and BDNF-related markers, such as the sBDNF level and the BDNF Val66Met polymorphism, might provide a useful predictor of acute SI in ACS patients." (PMID 35459929, 2022). "We hypothesized that diabetes might predispose impaired neural BDNF/TrkB signaling and activated neural apoptotic pathways in diabetic cerebral cortex, which above effects may be reversed following exercise training." (PMID 35743182, 2022). "Moreover, it was observed that depressed patients with type 2 diabetes mellitus display augmented miR-128 and cortisol blood levels associated to reduced levels of BDNF and shortened telomeres." (PMID 34829888, 2021). "BDNF is a neurotrophin essential for synaptic function, neural plasticity, and survival that has been linked to AD and other neurodegenerative diseases affecting cognition in diabetes." (PMID 35058808, 2021). "Additionally, BDNF showed a significant association with traditional risk factors, including diabetes, hypertension, smoking, physical activity, and obesity." (PMID 33004884, 2020). "The studies above suggest that a low level of BDNF may be a risk factor of diabetic neurovascular complications and that the administration of exogenous BDNF may have a role in the treatment of diabetes complications." (PMID 32012942, 2020). "In a rodent model of uncontrolled insulin‐deficient diabetes, Meek and colleagues report that infusion of BDNF to either the lateral cerebral ventricle or the VMH attenuates diabetic hyperglycemia via an insulin‐independent inhibition of hepatic glucose production." (PMID 30585393, 2019). "Longer intervention duration might have allowed a better quantification of trajectories and possible temporal sequencing of changes in BDNF and diabetes risk factors, which should be explored in future research." (PMID 30363954, 2018). "Resting serum BDNF levels and diabetes risk factors, such as fasting glucose, insulin, homeostasis model assessment (HOMA-B—beta cell insulin secretory capacity) and (HOMA-IS—insulin sensitivity), and hemoglobin A1c (HbA1c), were measured after an overnight fast at baseline and 6 months." (PMID 30363954, 2018). "The diabetes-induced down-regulation of BDNF and TrkB expression may be associated with diabetes-induced colon dysfunction." (PMID 29930382, 2018). "Treatment of diabetic rats with NSCs prevented the decrease in BDNF levels caused by diabetes." (PMID 28341839, 2017). "Moreover, a metabotrophic role of NGF and BDNF has recently been implicated in the pathogenesis of diabetes related disorders." (PMID 28122008, 2017). "Data from animal experiments and human studies suggested that BDNF may contribute to glucose metabolism and have a pathogenic role in the development of type 2 diabetes mellitus (T2DM) in humans." (PMID 25587547, 2014). "Moreover, a previous study also documented that inhibition of ERK activation in the retina by lutein blocks the actions of diabetes that cause BDNF depletion and synaptophysin reduction." (PMID 24347828, 2013). "Furthermore, in diabetic populations, reduced serum BDNF levels are significantly associated with impaired glucose metabolism, and this association may further exacerbate the progression of diabetes and its complications." (PMID 40933306, 2025). "Additionally, studies indicate that a reduction in BDNF levels past a certain limit may negatively affect glucose metabolism, thus raising the risk of diabetes and its associated complications." (PMID 40933306, 2025). "Research indicates that the BDNF Val66Met polymorphism may modulate cardiometabolic markers, such as the dietary insulin index and dietary insulin load, particularly in individuals with diabetes." (PMID 38988887, 2024).
diabetes (continued). "The alterations observed in the expression of Tnf-α, F4/80, Il-6, Tgf-β1, Igf-1, and BDNF could predispose to the disruption of uninjured skin homeostasis, suggesting that these alterations are the primary cause of impaired wound healing in diabetes." (PMID 36722656, 2023). "Additionally, higher BDNF methylation was associated with high fasting insulin levels, supporting the hypothesis that BDNF methylation plays important role in diabetes progression." (PMID 35225959, 2022). "Therefore, restoration of the redox state in diabetes may restore low BDNF levels, which can prevent complications associated with diabetes and the development of neurodegenerative diseases." (PMID 32405353, 2020). "Biochemical analysis revealed that diabetes induction reduced hippocampal BDNF and insulin levels and increased oxidative stress and inflammatory cytokines." (PMID 42222854, 2026). "The potential relationship between diabetes and serum BDNF suggests a possible interaction between diabetes and brain function." (PMID 41142318, 2025). "It is well established that general biological processes, such as hyperglycemia and kidney function disorders in type 2 diabetes mellitus, can lead to alterations in the concentration of BDNF in serum." (PMID 41142318, 2025). "The interconnections between micronutrient status, inflammatory activity, and BDNF are crucial for understanding the progression of diabetes." (PMID 41142318, 2025). "Similarly, BDNF concentrations in healthy individuals typically range 32.69 ± 8.33 ng/mL, but both T1D and T2D patients exhibit lower circulating BDNF levels, suggesting that BDNF deficiency may contribute to impaired bone remodeling and neuro-metabolic dysfunction in diabetes." (PMID 40568561, 2025). "Estrogen also promotes BDNF expression via the classical ERα-mediated transcriptional pathway, potentially impacting diabetes-related neurocognitive outcomes." (PMID 40426650, 2025). "Insulin resistance appears to affect and be related to the amount and function of BDNF in diabetes as T2DM patients demonstrate a drop of BDNF in their circulation in accordance with our study in rat group." (PMID 40088335, 2025). "In diabetes, chronic hyperglycemia induces oxidative stress and neuroinflammation, leading to a reduction in BDNF expression and alterations in AChE activity, both of which contribute to memory deficits and impaired executive function." (PMID 40726602, 2025). "The administration of various neurotrophic factors, including BDNF, exerts neuroprotective effects in animal models of diabetes and also prevents preexisting retinal dysfunctions from worsening in diabetic patients." (PMID 40003672, 2025). "Zinc similarly curbs oxidative damage and inflammation in diabetes, and supplementation raises BDNF levels, supporting neuronal health." (PMID 41142318, 2025). "Generally, participants without chronic conditions (e.g., hypertension, cardiovascular disease, cancer, diabetes and chronic respiratory disease) displayed slightly higher BDNF concentrations." (PMID 40222813, 2025). "Despite BDNF’s neuroprotective roles in diabetes, it has been noticed that hyperglycemia induces numerous alterations and the downregulation of BDNF expression, also partially mediated by the TrkB levels." (PMID 40003672, 2025). "As a result, conditions like diabetes and atherosclerosis typically present both heightened inflammation and reduced BDNF." (PMID 41142318, 2025). "A study examining BDNF concentrations among older adults with diabetes in China showed that those with T2DM had significantly lower BDNF levels than healthy individuals, and females had higher levels than males." (PMID 40933306, 2025). "In diabetes, chronic inflammation—with elevated IL-6, IL-12, IL-1β, and other cytokines—directly suppresses BDNF expression and signaling." (PMID 41142318, 2025).
diabetes (continued). "Moderate exercise lowers fasting glucose and HbA1c, up-regulates BDNF, improves insulin sensitivity and restores brain insulin signalling, directly counteracting these diabetes-specific insults." (PMID 41460428, 2025). "Within the field of diabetes research, BDNF is considered a crucial element in enhancing glucose metabolism and insulin sensitivity, serving as an essential mediator in the pathophysiological mechanisms underlying T2DM." (PMID 40933306, 2025). "Engaging in exercise has been proven to greatly enhance muscle strength in individuals with diabetes and boost BDNF expression." (PMID 40933306, 2025). "BDNF also lowers elevated blood glucose andimproves lipid metabolism, effectively preventing the progression of prediabeticmice to clinical diabetes." (PMID 41523972, 2025). "As a conserved serine/threonine kinase, AMPK regulates glucose and lipid metabolism, promotes hippocampal BDNF induction, and plays a key role in managing diabetes and its complications." (PMID 40426650, 2025). "As far as we are concerned, research on BDNF in diabetes has hardly been explored in an Indian scenario, which adds a unique aspect to this research." (PMID 39712817, 2024). "Injection of insulin as treatment for diabetes induces neurotrophic factors (BDNF) in hippocampus which has an improving effect on memory performance of Morris water maze test." (PMID 38528644, 2024). "The same literature review reported a rat model of diabetes and observed that chronic heavy alcohol consumption reduced Brain-derived neurotrophic factor (BDNF) levels." (PMID 39664526, 2024). "This is in line with the findings that there is an inverse correlation between serum BDNF levels and long-standing diabetes, in males and aged T2DM patients." (PMID 38648255, 2024). "BDNF plays a crucial role in pre-diabetes and T2DM cognitive impairment, whereserum levels are considerably increased in T2DM patients." (PMID 39077334, 2024). "Diabetes worsens the degeneration of the peripheral nervous system by diminishing the transmission of brain-derived neurotrophic factor (BDNF), NGF, and neurotrophin-3 in peripheral nerves, as well as reducing the secretion of insulin-like growth factors." (PMID 39050683, 2024). "The levels of BDNF in both serum and aqueous humor are significantly reduced in patients with diabetes mellitus prior to the onset of clinical signs of retinopathy." (PMID 38743493, 2024). "The fact that the pancreas, liver, and brain tissues all produce BDNF raises the possibility that type 2 diabetes Mellitus cognitive dysfunction, altered consciousness, and acquiring knowledge deficits are brought on by a BDNF shortage." (PMID 37287291, 2024). "In linear regression analysis, diabetes and platelet variables were found to be significant in predicting BDNF level." (PMID 36936159, 2023). "The papers focusing on at least one of the forms of garlic compounds for managing diabetes, DR, and BDNF/VEGF level were included in the present study." (PMID 36803536, 2023). "We also observed different distributions of BDNF patterns among diabetes groups in relation to cognition." (PMID 36936159, 2023). "The MoCA scores and BDNF levels were compared between diabetes groups after adjusting for age, gender, and education using ANCOVA." (PMID 36936159, 2023). "Serum BDNF levels of the patients were compared between diabetes groups (T2DM, PreDM and Control) and cognitive groups (IC-NC)." (PMID 36936159, 2023). "Osthole treatment data showed decreased the P2X4 receptor upregulation and SGC activation in DRG neurons, followed by the down-regulation of IL1β, TNF-α, BDNF and p-p38MAPK and the up-regulation of IL-10 in diabetic mellitus (DM) rats." (PMID 37151956, 2023). "We analyzed correlations between BDNF levels and patient sex, age, seizures, smoking, diabetes mellitus (DM), and the use of selected antiepileptic drug (AED) and antihypertensive drug groups." (PMID 38050515, 2023).